CDK4 (cyclin dependent kinase 4)
Diseases named in the same sentence as CDK4 in open-access papers (continued):
Sharing a sentence is not in itself a finding about the gene and the disease.
pancreatic cancer (92 papers, 2010 to 2026). "On the contrary, CDK4/CDK6 inhibitors have even been shown to sensitize RAS G12V-mutated cells against chemotherapeutic agents in pancreatic cancer." (PMID 35804842, 2022). "The aim of this article is to analyze the tissue expression of EGFR, Beta catenin, cyclin D1, CDK4, and ErbB2 in pancreatic cancer in order to find their association with the mortality and survival of patients with this tumor." (PMID 35448172, 2022). "The molecular mechanism of the various fate of pancreatic cancer cells upon CDK4/6 inactivation is associated with the modulation of CDK2 activity." (PMID 30340359, 2018). "It was also demonstrated that Antp-TPR peptide had a significant antitumor activity in mice xenografted with human pancreatic cancer (BXPC3) causing loss of CDK4, which is one of Hsp90 client proteins in tumors." (PMID 21235734, 2011). "Both types of altered genotype, CDKN2A and CDK4, have a higher risk for pancreatic cancer." (PMID 38607041, 2024). "Treatment of pancreatic cancer cells with pristimerin also resulted in G1-phase arrest which was strongly associated with a marked decrease in the level of cyclins (D1 and E) and cyclin-dependent kinases (cdk2, cdk4 and cdk6 ) with concomitant induction of WAF1/p21 and KIP1/p27." (PMID 22952775, 2012). "One of the best characterized dependencies involves cell cycle regulation, potentially explaining why the combination of selective G12C inhibitors with CDK4/6 inhibitors presents a synergistic activity in preclinical models of pancreatic cancer and NSCLC." (PMID 40940900, 2025). "The cell cycle, together with PI3K/AKT signaling, the DNA damage response and repair, and autophagy were confirmed as most important nodes synergizing with CDK4/6 inhibitors in a CRISPR-Cas9 screen of pancreatic cancer cells." (PMID 40699853, 2025). "Multiple direct CDK4/6 inhibitors have been developed and tested in clinical trials for pancreatic cancer." (PMID 39123441, 2024). "Our novel study highlights the synergistic therapeutic potential of the novel combination of Abe, a CDK4/6 inhibitor, and Pan, an HDACi when tested in vitro in highly aggressive pancreatic cancer cells." (PMID 39123441, 2024). "The aberrant activation of the cyclin-dependent kinase 4/cyclin D1 pathway is reported frequently in pancreatic cancer due to the overexpression of D-type cyclin proteins." (PMID 39123441, 2024). "Due to the amplification of acquired CCNE1 in breast and pancreatic cancers, the cells have acquired resistance to CDK4/6 inhibitors in vitro, damaging the sensitivity of cells to CDK4/6 inhibitors but still rendering them sensitive to CDK2 inhibitors." (PMID 39648148, 2024). "Combination of MEK and CDK4/6 inhibitors in KRAS-positive pancreatic cancer induced cancer cell senescence and created a physiological stress response that activated endothelial cells and sensitized tumors to PD-1 checkpoint blockade." (PMID 39286984, 2024). "Consistently, CDK4/6i increases mitochondrial metabolism in BrafV600E melanoma cells and pancreatic cancer." (PMID 39695080, 2024). "The downregulation of GINS2 in pancreatic cancer cells resulted in a significant downregulation of CDK4/6." (PMID 38467631, 2024). "In pancreatic cancer models, data have been variable, with several studies demonstrating mono-therapy activity of CDK4/6is, but inherent resistance was also described." (PMID 36765923, 2023). "Another study also demonstrated the inhibition of Hsp90 by withaferin A in a pancreatic cancer cell line through the degradation of Akt, cyclin-dependent kinase 4 Cdk4, and a glucocorticoid receptor of Hsp90 client protein by an ATP-independent mechanism." (PMID 37259311, 2023). "Palbociclib is a CDK4/6 inhibitor that can inhibit cell cycle progression and has been shown to regulate the immune characteristics of pancreatic cancer cells in patient-derived xenograft models." (PMID 36981005, 2023).
pancreatic cancer (continued). "PLK inhibitors were shown to be effective in ER-positive breast cancers that were resistant to CDK4/6 inhibition, however other studies showed antagonism in pancreatic cancer." (PMID 37126527, 2023). "A recent study took a similar approach; bempedoic acid in combination with cell cycle kinase inhibitors (palbociclib targeting CDK4/6) reduced cell viability and invasion in a panel of breast and pancreatic cancer cell lines." (PMID 37958642, 2023). "Second, the small sample size affects the reliability of the conclusions, although this is the largest study of trametinib in combination with HCQ or CDK4/6 inhibitors in pancreatic cancer." (PMID 37817078, 2023). "We also tested the therapeutic effect of CDK4/6 inhibitors in SEMA6C-low pancreatic cancer, which exhibited increased cyclin D1 expression." (PMID 35269749, 2022). "Overexpression of INSM1 inhibits the binding of cyclin D1 and CDK4, induces cell cycle arrest, and inhibits the growth of panc-1 pancreatic cancer cell line." (PMID 36531655, 2022). "Our study has provided a direct association between pancreatic cancer survival and the overexpression of EGFR, beta-catenin, cyclin D1, CDK4, and ErbB2." (PMID 35448172, 2022). "The results of WB indicated that in the radioresistant pancreatic cancer cells, the cyclin D1, Bax, CDk4, cleaved caspase-3, Bcl-2, and γ-H2AX proteins were upregulated to varying degrees." (PMID 36276285, 2022). "In this article, the combination of palbociclib, a CDK4/6 inhibitor, and nab-paclitaxel in advanced pancreatic cancer evaluates an important drug combination using translational science." (PMID 36970055, 2022). "CDK4 is a key regulator of the G1 phase of the cell cycle and has been shown to be overexpressed in pancreatic cancer." (PMID 33507917, 2021). "Pancreatic cancer cells react to CDK4/6 inhibition with enhanced oxidative phosphorylation, associated with an RB-dependent increase in mitochondrial mass and mTORC1 activation." (PMID 34248938, 2021). "Here, we demonstrated that when expressed in p16-null pancreatic cancer cells, p16-L16R had little ability to suppress the cell cycle and exhibited decreased binding to CDK4 and CDK6 compared with p16-WT." (PMID 33823155, 2021). "Abnormal high expression of CCND1 or CDK4 has been found in various tumors, such as pancreatic cancer, bladder cancer and gastric cancer." (PMID 32742488, 2020). "Although this strategy showed translational potential, genomic analyses suggest that the conventional CDK4/6–RB1 signaling pathway is divergent in pancreatic cancer, questioning the efficacy of this therapy." (PMID 33282875, 2020). "The utility of targeting CDK4/6 as a strategy for targeted-immunotherapy in pancreatic cancer now warrants further exploration." (PMID 33282875, 2020). "A recent report proposed that a “tailored” combination of first-line and second-line CDK4-targeting drugs would hold promise for pancreatic cancer treatment." (PMID 33282875, 2020). "Herein, we reveal multiple new facets of the CDK4/6–RB1 axis in pancreatic cancer, highlighting the complexity of this signaling axis for future prognostic and therapeutic targeting." (PMID 33282875, 2020). "Genomic analyses indicated that a similar phenotype exists in pancreatic cancer in which CDK4 regulates RB1 activation." (PMID 33282875, 2020). "These compounds use less binding energy to CDK4 and inhibit its activity, suggesting them as potential drugs for treating pancreatic cancer." (PMID 30104534, 2018). "Clinical studies have demonstrated a correlation between cyclin-dependent kinase 4 (CDK4) and malignant progression of pancreatic cancer." (PMID 30104534, 2018). "The work herein demonstrates that our patient-derived models of PDA share remarkably similar biology to their pancreatic tumor of origin, and that in these models, CDK4/6 inhibition leads to potent suppression of tumor growth." (PMID 26158861, 2015).
pancreatic cancer (continued). "Surprisingly, in work published by several groups, single agent CDK4/6 inhibition had a particularly weak effect in models of pancreatic cancer." (PMID 26158861, 2015). "Despite limited efficacy in established cell line models, this data suggests that CDK4/6 inhibitors should be considered for inclusion into emerging pancreatic cancer clinical trials." (PMID 26158861, 2015). "Eight pancreatic cancer cell lines were screened for their proliferative response to CDK4/6 inhibition." (PMID 25156567, 2014). "Our results demonstrated that frankincense essential oil suppresses cyclin D1 and cdk4 proteins expression in pancreatic cancer cells." (PMID 23237355, 2012). "Essential oil activated the caspase-dependent apoptotic pathway, induced a rapid and transient activation of Akt and Erk1/2, and suppressed levels of cyclin D1 cdk4 expression in cultured pancreatic cancer cells." (PMID 23237355, 2012). "Next, we investigated the levels of pro-apoptotic Bim, E-cadherin, cyclin B1, and CDK4, which are known to play a critical role in regulating the proliferation, differentiation and apoptosis of pancreatic tumors." (PMID 22509328, 2012). "We observed that the treatment of pancreatic cancer cells with honokiol resulted in G1-phase arrest of cell cycle progression, along with reduction in cyclin D1, cyclin E, Cdk2 and Cdk4 and increase in p21 and p27 at the protein level." (PMID 21720559, 2011). "Recently, overexpression of AP-2α in pancreatic cancer cells was shown to reduce tumor growth through an altered expression pattern of cell cycle-controlling factors such as CDK-4, CDK-6, cyclin-G1, p27kip1 and p57kip2." (PMID 20805990, 2010). "Overexpression of AP-2α in pancreatic cancer cells was shown to reduce tumor growth through an altered expression pattern of cell cycle-controlling factors such as CDK-4, CDK-6, Cyclin-G1, p27kip1 and p57kip2." (PMID 20805990, 2010). "The inhibition of HDAC and CDK4 leads to apoptotic cell death in pancreatic cancer." (PMID 39123441, 2024). "CDK4/6 inhibitors in combination with phosphatidylinositol 3‐kinase (PI3K)/mTOR or TGFβ receptor type I (TGFβ‐RI) inhibitors have confirmed efficacy in preclinical pancreatic cancer models." (PMID 37840530, 2023). "Our finding that SEMA6C-low pancreatic cancer showed increased cyclin D1 expression motivated us to test whether CDK4/6 inhibitors may have therapeutic benefits on pancreatic cancer with the downregulation of SEMA6C." (PMID 35269749, 2022). "Notably, elevated OXPHOS was also induced by ribociclib and abemaciclib, indicating similar metabolic effects of different CDK4/6 inhibitors at least in the context of pancreatic cancer." (PMID 33572972, 2021). "This review provides a brief overview of preclinical and clinical studies focusing on novel therapeutic options concerning specific KRAS, CDK4/6 inhibitors, and combination of immune checkpoint inhibitors with chemo or molecular targeted agents for the treatment of pancreatic cancer." (PMID 34440587, 2021). "Since G2M pathway score can accurately assess the cell cycle activity, we cannot help but speculate that the score may be useful as a biomarker for patient selection for CDK4/6 inhibition for pancreatic cancer." (PMID 33036243, 2020). "Thus, the overall impact of a positive genetic testing for CDKN2A/CDK4 in the early detection and improved outcome of internal cancers and, in particular, of pancreatic cancer remains undetermined." (PMID 29774366, 2018). "Thus, it was unexpected that multiple established pancreatic cancer cell models would exhibit a relatively weak response to pharmacological CDK4/6 inhibit." (PMID 26158861, 2015).
pancreatic cancer (continued). "In addition, frankincense essential oil modulated expression of cell cycle regulator proteins, cdk4 and cyclin D1 (crucial cell cycle regulators), in pancreatic cancer cells." (PMID 23237355, 2012). "Frankincense essential oil suppressed cyclin D1 and cdk4 expression may lead to suppressed Rb phosphorylation which results in suppressed cell cycle progression in pancreatic cancer cells." (PMID 23237355, 2012). "Depletion of RLIP76 by antisense significantly increased the levels of the pro-differentiation marker E-cadherin and pro-apoptotic protein Bim while decreasing the levels of anti-apoptotic protein Bcl2, cyclin B1 and CDK4 in both BxPC3 and Panc-1 pancreatic cancer cells." (PMID 22509328, 2012). "Our data revealed a dose-dependent decrease in the expression of cyclins (D1 and E) and cyclin-dependent kinases (Cdk2 and Cdk4); while an induced expression of cyclin-dependent kinase inhibitors (p21 and p27) was observed after honokiol treatment in both MiaPaCa and Panc1 pancreatic cancer cells." (PMID 21720559, 2011). "In addition, CDK4 activity might play a role in pancreatic cancer cell growth from the performance of active compounds in both in vitro anticancer activity and CDK inhibition pattern." (PMID 36656085, 2023). "Indeed, chemotherapy-induced resistance via CDK4 amplification, RB loss, and cyclin E1 amplification has been suggested to contribute to the lack of efficacy of palbociclib in pancreatic cancer when given as the third or fourth line of treatment." (PMID 36970055, 2022). "The observation that CDK4/6 inhibition may give rise to drug tolerance warrants additional studies to assess whether the timing of drug administration can ameliorate this effect of ribociclib, as has been proposed for palbociclib in pancreatic cancer." (PMID 34944934, 2021). "Furthermore, Chou and collaborators showed that inhibition of CDK4 with palbociclib significantly induces apoptosis in pancreatic tumour overexpressing Rb and also enhances the apoptotic effect of chemotherapeutic gemcitabine in patient-derived xenografts in mice." (PMID 30340359, 2018). "In conclusion, E2F1 promotes pancreatic cancer cell proliferation and cell-cycle progression by upregulating WDHD1, which in turn enhances the expression of the CDK4-cyclin D1 complex." (PMID 42041705, 2026). "Combining a multi-selective RAS(ON) inhibitor with CDK4/6 inhibition and CD40 agonism shifts drug-tolerant persister cells towards senescence and promotes durable tumor regression in pancreatic cancer." (PMID 40299790, 2025). "CDK4/6-E2F1 mediates an increase in MAGED1 expression, which promotes FBP1 degradation and the Warburg effect in pancreatic cancer." (PMID 40307228, 2025). "We studied the effects of the combination of Abe, a CDK4/CDK6 inhibitor, and Pan, a pan-HDAC inhibitor (HDACi), on pancreatic cancer cells." (PMID 39123441, 2024). "Cyclin dependent kinase 4/6 (CDK4/6) inhibitors, in combination with MAPK inhibitors, induced senescence in lung and pancreatic cancer mouse models, and the SASP contributed to a potent antitumor immune response." (PMID 38195762, 2024). "Preclinical models of pancreatic cancer (PDAC) suggest a synergistic role for combined MEK and autophagy signaling inhibition, as well as MEK and CDK4/6 pathway targeting." (PMID 39352477, 2024). "Previous studies reported that CDK4/6 inhibitors also suppressed PDAC cell proliferation in vitro and in vivo, and some ongoing clinical trials are testing their efficacy in pancreatic cancer (ClinicalTrials.gov Identifier: NCT03065062, NCT04870034)." (PMID 37198667, 2023). "More recently, preclinical and clinical reports suggested synergism between CDK4/6 and RAF/MAPK pathway inhibitors, including modulation of the tumor and immune microenvironment, and antitumor responses were observed in pancreatic cancer patients." (PMID 37840530, 2023).
pancreatic cancer (continued). "Inhibition of CDK4/6 and lysosome function overcomes c-MYC–mediated cell cycle entry in the face of trametinib and chloroquine co-treatment in pancreatic cancer." (PMID 36719686, 2023). "A combination of CDK4/6 inhibitors and MEK inhibitors inhibited growth and increased apoptosis in PDAC cell lines and patient-derived models of pancreatic cancer." (PMID 36765923, 2023). "Drugs targeting the cyclin-dependent kinase 4/6 (CDK4/6)–retinoblastoma 1 (RB1) axis have shown efficacy against multiple solid cancers, but their therapeutic potential in pancreatic cancer remains poorly defined." (PMID 33282875, 2020). "In light of this, we analyzed relevant genomic data and observed the opposite effects of CDK4 and CDK6 on pancreatic cancer prognosis." (PMID 33282875, 2020). "The approach of CDK4/6 inhibition by palbociclib was also evaluated in combination with IGF1 receptor inhibitors and patient-derived models of pancreatic cancer primary tumour explants." (PMID 30340359, 2018). "We previously demonstrated that GSK3β sustains expression of CDK4, CDK6, and cyclin D1, which results in phosphorylation-dependent inactivation of RB cell cycle regulator, in CRC and pancreatic cancer cells." (PMID 29568361, 2018). "We also found that DHA down-regulated cdks and cyclins, such as Cdk4, Cdk6, and cyclin E, which play essential roles in the regulation of cell cycle progression; DHA thus increased G0/G1 cell cycle arrest in pancreatic cancer cells." (PMID 27613829, 2016). "Cdk4, Cdk6, E2F3, and E2F1 play key roles in the regulation of cell cycle progression in pancreatic cancer." (PMID 27613829, 2016). "Down-regulation of Cdk4, Cdk6, E2F3, and E2F1 expression increases G0/G1 cell cycle arrest in pancreatic cancer cells." (PMID 27613829, 2016). "MiR-192 overexpression diminished the expression of p21Cip1, p27Kip1, p107, p130 and retinoblastoma-1 tumor suppressor protein (Rb1) and increased the expression of cyclin D1, cyclin D2, CDK4, CDC2, and SKP-2 in both pancreatic cancer tissues and cell lines." (PMID 27240340, 2016). "Overexpression of cyclin D1/CDK4 is regulated by CEACAM6 and promotes cell proliferation in human pancreatic carcinoma." (PMID 27818681, 2016). "The observed inhibitory effects of pristimerin on cyclin D1, cyclin E, cdk2, cdk4 and cdk6, along with its upregulating effects on WAF1/p21 and KIP1/p27 in pancreatic cancer cells suggest its potential in disruption of the uncontrolled cell cycle progression." (PMID 22952775, 2012). "In all four pancreatic cancer cell lines tested, we found decreased expression of cell cycleproteins, including E2F1, Cyclin D1, Cyclin E, Cdk2, Cdk4 and Cdk6, and increased expression of p21 and p27." (PMID 23028659, 2012). "In pancreatic cancer, CBX3 downregulates FBP1 expression and promotes glycolysis, while the CDK4/6-E2F1 pathway increases MAGED1 expression and promotes FBP1 degradation, and the CDK4/6 inhibitor PD0332991 eliminates the Warburg effect." (PMID 40100307, 2025). "For example, Dinaciclib is a multi-CDK inhibitor that does not act against CDK4/6, and it has shown efficacy in pancreatic cancer in vitro and in vivo mouse model systems." (PMID 38607041, 2024). "Similar to pancreatic cancer, monotherapy with CDK4/6 inhibitors did not lead to positive outcomes in the treatment of hereditary melanoma." (PMID 38137564, 2023). "The results demonstrated that silencing circSEC24A expression resulted in protein downregulation of CDK4, CDK6 and Cyclin D1, indicating that inhibited circSEC24A could negatively modulate pancreatic cancer cell proliferation." (PMID 34906151, 2021). "CDK4 has been evaluated extensively in mesothelioma, HCC, and pancreatic cancer." (PMID 32033319, 2020). "LY2835219 inhibits CDK4/6 leading to reduced tumour growth in human xenografts, however, not demonstrated up until now for pancreatic cancer." (PMID 30340359, 2018).